TTI2 (TELO2 interacting protein 2)
Description:
Regulator of the DNA damage response (DDR). Part of the TTT complex that is required to stabilize protein levels of the phosphatidylinositol 3-kinase-related protein kinase (PIKK) family proteins. The TTT complex is involved in the cellular resistance to DNA damage stresses, like ionizing radiation (IR), ultraviolet (UV) and mitomycin C (MMC). Together with the TTT complex and HSP90 may participate in the proper folding of newly synthesized PIKKs.
Synonyms: C8orf41; FLJ23263; MRT39
Tractability: Small molecule: a structure with a bound ligand is known. PROTAC: ubiquitination databases record sites on it; its protein half-life has been measured.
Gene: Protein-coding gene on chromosome 8 (33,473,386 to 33,513,185, reverse strand). Ensembl gene ENSG00000129696.
Subcellular location (Human Protein Atlas): Centrosome; Nucleoplasm
Gene Ontology:
Biological process: positive regulation of DNA damage checkpoint; protein stabilization
Cellular component: TTT Hsp90 cochaperone complex; nucleus
Genetic constraint (gnomAD): Loss-of-function variants: 26 observed, 47.6 expected, observed/expected ratio (o/e) 0.55, 90% interval 0.4 to 0.76. The upper end of that interval is the gene's LOEUF score, 0.76, which puts it in group 3 of 6, group 1 being the genes least tolerant of losing a copy. Missense variants: 582 observed, 648.43 expected, observed/expected ratio (o/e) 0.9, 90% interval 0.84 to 0.96. Synonymous variants: 254 observed, 267.78 expected, observed/expected ratio (o/e) 0.95, 90% interval 0.86 to 1.05.
Homologues: Orthologues: chimpanzee TTI2 (98% identical), macaque FUT10 (88% identical), pig TTI2 (78% identical), dog TTI2 (77% identical), rabbit TTI2 (74% identical), mouse Tti2 (72% identical), guinea pig TTI2 (70% identical), rat Tti2 (68% identical), zebrafish tti2 (39% identical).
Diseases named in the same sentence as TTI2 in open-access papers:
TTI2 is named in the same sentence as 13 diseases in open-access papers, as found by Europe PMC text mining. Sharing a sentence is not in itself a finding about the gene and the disease. The quoted sentences say what the papers report.
Intellectual disability (4 papers, 2019 to 2022). "In humans, homozygous and compound heterozygous loss-of-function mutations in TTI2 cause microcephaly, severe intellectual disability, dysmorphic facial features, short stature, speech and movement disorders, and skeletal deformations." (PMID 35377872, 2022). "We report a novel loss-of-function homozygous variant in TTI2 that leads to syndromic intellectual disability and primary microcephaly." (PMID 35990009, 2022). "Herein, we identified compound heterozygous mutations in TTI2 using whole-exome sequencing (WES) in a Chinese family with a recessive inheritance pattern of syndromic intellectual disability." (PMID 31737043, 2019).
microcephaly (3 papers, 2019 to 2022). A congenital or acquired developmental disorder in which the circumference of the head is smaller than normal for the person's age and sex. "We described the first French Canadian case with primary microcephaly and global developmental delay secondary to a new D317V homozygous mutation in TTI2 gene." (PMID 32061250, 2020). "Our patient highlights the importance of TTI2 protein in normal brain development and increases the phenotypic description of TTI2 related microcephaly." (PMID 32061250, 2020).
Primary microcephaly (2 papers, 2020 to 2022). Head circumference below 2 standard deviations below the mean for age and gender at birth. "Here, we report a child with primary microcephaly carrying D317V Homozygous mutation in TELO2-interacting protein 2 (TTI2) gene, identified by whole-exome sequencing (WES)." (PMID 32061250, 2020).
autosomal recessive primary microcephaly (1 paper, 2018). Autosomal recessive primary microcephaly (MCPH) is a rare genetically heterogeneous disorder of neurogenic brain development characterized by reduced head circumference at birth with no gross anomalies of brain architecture and variable degrees of intellectual impairment. "Mutations in the TTI2 gene have been associated with autosomal recessive ID and the ASPM gene has been implicated in autosomal recessive primary microcephaly-5." (PMID 29794985, 2018).
brain cancer (1 paper, 2022). A primary or metastatic malignant neoplasm affecting the brain. "Additionally, TTI2 in prostate, APC in breast, MAD2L2 in pan-cancer, HERC2 in prostate, and MDN1 in brain cancer associated with the mutation component dMMRICA." (PMID 35764656, 2022).
frontotemporal dementia (1 paper, 2022). Frontotemporal dementia (FTD) comprises a group of neurodegenerative disorders, characterized by progressive changes in behavior, executive dysfunction and language impairment, as a result of degeneration of the medial prefrontal and frontoinsular cortices. "In humans, more than 800 genomic variants are linked to TTI2 expression, seven of which have associations to protein and blood stem cell factor concentrations, blood pressure and frontotemporal dementia." (PMID 35377872, 2022). "Mining human data sets revealed more than 800 genomic variants that are linked to TTI2 expression, seven of which refer to associations with protein and blood stem cell factor concentrations, blood pressure, and frontotemporal dementia." (PMID 35377872, 2022).
Insulin resistance (1 paper, 2022). Increased resistance towards insulin, that is, diminished effectiveness of insulin in reducing blood glucose levels. "However, reducing Tti2 expression by half led to a reduction of the number of new neurons in the DG, a concomitant lowering of serum glucose and insulin concentrations, and to hallmarks of insulin resistance in skeletal muscles." (PMID 35377872, 2022).
cancer (4 papers, 2019 to 2025). A tumor composed of atypical neoplastic, often pleomorphic cells that invade other tissues. "Several observations also support a likely involvement of FUT10 and TTI2 in cell cycle as well as cancer." (PMID 31384924, 2019). "WAC expression was also correlated with that of RPAP3 and PIH1D1 (in three out of 10 cancer types), components of R2TP, and we also found some correlation with TTI2." (PMID 40653822, 2025).
TTI2 also shares sentences with these, for which no sentence is quoted: autosomal recessive syndromic intellectual disability (1 paper); Cognitive impairment (1); developmental delay (1); Glucose intolerance (1); movement disorder (1).